CSF1 (colony stimulating factor 1)
Diseases named in the same sentence as CSF1 in open-access papers (continued):
Sharing a sentence is not in itself a finding about the gene and the disease.
cancer (continued). "Understanding the signaling mechanism of CSF-1 and CSF-1R in cancer and other diseases and taking appropriate measures to block CSF-1/CSF-1R signaling is a promising new immunotherapy with potential for future clinical application." (PMID 34729112, 2021). "H27K15 is a novel competitive monoclonal antibody for CSF‐1 blockage that has been generated for cancer immunotherapy." (PMID 33463063, 2021). "Increasing research has shown that CSF-1 and CSF-1R are expressed in malignant tumors of the digestive tract and can promote the growth, migration and invasion of tumors." (PMID 34729112, 2021). "Blocking CSF-1R with antibodies can reduce the activation of CSF-1 and prevent the proliferation and metastasis of malignant tumors." (PMID 34729112, 2021). "Targeted inhibition of the CSF-1/CSF-1R signal axis has broad application prospects in cancer immunotherapy." (PMID 34729112, 2021). "Enrichment analysis of 50 cancer hallmarks and 132 immune signaling modules showed that CSF-1, MYC, TGF-β, JAK/STAT3, IFN-α, and the other 29 signaling pathways were enriched in C2 versus C1 subtype (P < 0.05)." (PMID 34722280, 2021). "Targeting CSF1/CSF1R for M2 macrophage reprogramming has been widely performed in clinical trials for cancer therapy." (PMID 34248982, 2021). "Although previous studies have identified fibroblasts as a main source of inflammatory cytokines, including CSF1, CSF1 expression was observed both in cancer epithelial cells and in vimentin positive cells." (PMID 33643790, 2021). "This interaction is further promoted by a positive feedback loop whereby cancer cells produce CSF1 and TAMs express epidermal growth factor (EGF) which is a positive regulator of RhoA signaling." (PMID 34803925, 2021). "During the transition from benign growth to invasive tumor, colony stimulating factor-1 (CSF1) has been reported to be one of the key cytokines that regulates cancer-initiated inflammatory responses." (PMID 32724427, 2020). "Most of the genes in the subnetworks were inflammatory cytokines and participated in TNF signaling pathways and pathways in cancer, such as Ccl2, Ccl20, Csf1, Cx3cl1, Cxcl1, Cxcl3, Il6, Birc3, Map3k8, Nos2, Nfkb2, Tnfrsf1b, and Vcam1." (PMID 33042984, 2020). "Presumably, the reduction of CSF-1R expression in THP-1 cells led to a decreased response of the cells to CSF-1 secreted by cancer cells." (PMID 33156861, 2020). "In turn, cancer cells express colony stimulating factor 1 (CSF-1), also known as macrophage stimulation factor-1 (M-CSF), a powerful chemotactic molecule for TAMs, which express the colony stimulating factor 1 receptor (CSF1R)." (PMID 32867288, 2020). "Those compounds target chemokines, metalloproteinases, integrins, tyrosine kinases, interleukin-6, CSF-1 and TGFβ functions, produced or acting both in cancer cells and stromal cells." (PMID 32194848, 2020). "CSF-1/CSF-1R signaling facilitates recruitment and survival of TAMs within the tumor microenvironment in many cancers." (PMID 32194848, 2020). "For instance, tumors can early on secrete the colony-stimulating factor 1 (CSF-1 or M-CSF) that expands the pool of macrophages towards the cancer supporting TAM phenotype and later on the chemokine (C-C motif) ligand 2 (CCL2) that attracts monocytes." (PMID 30832375, 2019). "To evaluate 3D185’ potential advantage of dual targeting FGFR and CSF1R with equal potency, we further used a co-cultured context with FGFR3-driven RT112 cancer cell line and CSF-1-differentiated human macrophages." (PMID 31438996, 2019). "Some therapeutic strategies focusing on the blockade of the CSF-1 function were used in several models of cancer, resulting in delayed cancer development together with a decreased number of TAM." (PMID 30680411, 2019). "CCL8 treatment of both cancer cell lines significantly upregulated the expression of CSF1 mRNA and protein (Log2FC > 1, p < 0.05), as well as TNF-α and IL-1β." (PMID 30930117, 2019).
cancer (continued). "Our studies reveal the utility and complexity of single or combination therapeutics against CSF1 or IL34 as a bi-specific drug in inflammation or cancer." (PMID 31552020, 2019). "Kaplan-Meier survival curves showed that higher CSF-1 expression correlated with a significantly lower disease-free survival (P = 0.008) and cancer-specific survival (P = 0.001)." (PMID 31565097, 2019). "In the multivariate analysis, we found that cancer-specific survival was also related to CSF-1 expression (HR = 5.14, CI = 1.27‐20.84, P = 0.022)." (PMID 31565097, 2019). "CSF1 (M‐CSF) is a key regulator of monocyte recruitment and differentiation into TAMs,131 making CSF1/CSF1R signaling a potential therapeutic target for cancer immunotherapies." (PMID 30776148, 2019). "Anchored multiplex PCR (AMP) for next-generation sequencing utilizing a customized panel targeting 86 cancer-related genes was performed, and it identified novel non-CSF1-driven gene fusions: NIPBL-ERG, FN1-ROS1, and YAP1-MAML2." (PMID 31906059, 2019). "Our results also used univariate and multivariable analyses, which found that high CSF-1 expression was an independent predictor of poor disease-free survival (hazard ratio = 2.56; P = 0.007) and cancer-specific survival (hazard ratio = 5.14; P = 0.022)." (PMID 31565097, 2019). "Cancer cells recruit macrophages through Colony Stimulating Factor 1 (CSF1), and high CSF1 concentrations are correlated with poor prognoses." (PMID 30701168, 2019). "Our immunofluorescence staining in UTUC cancer cells also found CSF-1 to be prominently expressed in the nucleus." (PMID 31565097, 2019). "High CSF-1 expression was correlated with poor disease-free survival (P = 0.008) and cancer-specific survival (P = 0.001)." (PMID 31565097, 2019). "Consistent with this, CSF1 expression in human cancers is highest at the invasive edge where macrophages are most abundant." (PMID 29594035, 2018). "Here, we set out to evaluate the effects of IL-34 and CSF-1 on cancer cell migration in transwell assays." (PMID 29796177, 2018). "Cancer cells, in turn, express CSF1, which acts as a chemoattractant and chemokinetic molecule for CSF1R-expressing TAMs." (PMID 29584702, 2018). "As our understanding of the influence of CSF1/CSF1R-mediated signaling on human myeloid-derived cells other than macrophages is just emerging, the focus of this review is on TAM and current clinical efforts to specifically target CSF1/CSF1R in cancer therapy." (PMID 28716061, 2017). "The crosstalk between TAMs and cancer cells is required for invasion and metastasis, whereby cancer cells provide CSF1 for TAMs, and in turn TAMs produce EGF that feeds back on cancer cells to stimulate their movement." (PMID 29220404, 2017). "Among these genes, Csf1, a key factor for macrophage survival, was shown to be the main target gene, promoting metastatic growth once cancer cells seed into the lungs." (PMID 29212030, 2017). "Targeting CSF-1 has predominantly been described in cancer, where there appears to be an advantage when it is used in combination with other immune therapies." (PMID 29284500, 2017). "More importantly, high expression of miR-1207-5p or low expression of CSF1 provided better survival chance for NSCLC patients compared with cancer with low expression of miR-1207-5p or high expression of CSF1." (PMID 27107415, 2016). "In a NSCLC cancer specimen expression profile dataset (GSE31210,), cancer with low expression of CSF1 had better survival chance compared with cancer with high expression of CSF1 (P = 0.04)." (PMID 27107415, 2016). "As a growth factor, CSF1 is secreted by macrophages, epithelial and fibroblasts cells and cancer cells." (PMID 27107415, 2016). "Next, we used quantitative real-time PCR (qPCR) to measure miR-1207-5p and CSF1 expression levels in different cancer cell lines." (PMID 27107415, 2016).
cancer (continued). "Overexpression of CSF-1 and/or FMS has been implicated in a number of disease states such as in the growth and metastasis of certain types of cancer, in the promotion of osteoclast proliferation in bone osteolysis, and in many inflammatory disorders." (PMID 27736957, 2016). "CSF1 expression by macrophages, stromal cells and osteoclasts allows for important paracrine interactions between host microenvironment and cancer cells." (PMID 27107415, 2016). "CSF1 can stimulate cancer cells directly, and it also can promote tumorigenesis indirectly through mobilizing and adjusting the host immune system responding to cancer cells." (PMID 27107415, 2016). "In this study we aim to further understand the mutual effects between cancer cells and macrophages by investigating the role of CSF-1 and CCL2 stimulation on this interaction and promotion of an M2 phenotype within the context of canine mammary carcinoma." (PMID 26174804, 2015). "We have shown that CCL2 is required for driving LPS-induced activation of macrophages, and that CSF-1, secreted from cancer cells, induces polarisation of macrophages." (PMID 26174804, 2015). "CSF-1 overexpression and high densities of intra-tumoral macrophages are often considered as indicators of poor prognosis for cancer patients." (PMID 26337837, 2015). "This implies that cancer cell mediated effects on macrophages are at least partially dependent on CSF-1." (PMID 26174804, 2015). "TAMs express monocyte colony stimulating factor receptor (M-CSFR, also known as CSF-1R or cFMS), which binds monocyte colony stimulating factor (M-CSF, also known as CSF-1) secreted by cancer cells." (PMID 26243145, 2015). "We have shown that cancer cells and macrophages have mutual effects on each other, and that the cytokines CSF-1 and CCL2 are important mediators of this interaction." (PMID 26174804, 2015). "To investigate the role of CSF-1 in the interaction between cancer cells and macrophages, we utilised soluble recombinant canine CSF-1 receptor (rcCSF-1R) to competitively inhibit free CSF-1 in co-culture experiments with RAW cells and REM134 cells." (PMID 26174804, 2015). "A paracrine loop involving the production of EGF by macrophages and CSF-1 by cancer cells has been demonstrated." (PMID 26043921, 2015). "Yet treatment with IL-34 and co-culture with carcinoma cells partially rescued the anti-CSF-1 effects on MCs." (PMID 26098772, 2015). "Further, the expression of the alternative ligand IL-34 is organ specific and carcinoma cells produce significant amounts of CSF-1 as well as IL-34, which partially interferes with the anti-CSF-1 treatment effects." (PMID 26098772, 2015). "Colony stimulating factor 1 (macrophage) (Csf1) plays an important role in cancer metastasis and invasion." (PMID 25278030, 2014). "Additional results presented herein suggest a potential cross-talk between cancer cells and the microenvironment controlled by CSF1/Vav1 signaling pathways." (PMID 25313137, 2014). "Among the numerous possible candidates, we picked out the ones overexpressed in cancers and proliferation- and metastasis-associated genes, including NOTCH2, FGFR1, CSF1, AGAP2, CREB1, for further analysis." (PMID 24614175, 2014). "Elevated circulating levels of CSF-1 have also been reported in some neoplastic malignancies, including AML, and appear to be associated with poor prognosis, further promoting the use of the SJL/J mouse in the study of the CSF-1's role in cancer." (PMID 25062865, 2014). "Based on these findings we can conclude that the used CSF-1 dose mimicked the presence of macrophages in cancer cells environment regarding the CSF-1R signaling." (PMID 23561040, 2013). "The wound healing assay showed that in all examined cancer cell lines the knockdown of csf-1r decreased migratory abilities, whereas treatment with CSF-1 (25 ng/ml) increased migration." (PMID 23561040, 2013).
cancer (continued). "We showed that treatment of cells with CSF-1 as well as csf-1r knockdown had significant effect on cancer cells migration." (PMID 23561040, 2013). "We found that both: knockdown of csf-1r and an increase of its expression after CSF-1 treatment have a significant impact on cancer cells." (PMID 23561040, 2013). "Previous publications have noted that EGFR signaling regulates macrophage colony-stimulating factor-1 (MCSF-1) expression in murine cancer cells." (PMID 22276166, 2012). "EGF and CSF-1 are shown to stimulate invadopodia formation in cancer cells and podosome formation in macrophages, respectively." (PMID 21307399, 2010). "CSF-1 has been shown to be a major chemoattractant for macrophages, linked to TAM regulation of cancer progression in animals." (PMID 19696929, 2009). "Gene profiling of CT26 cancer cells also indicates upregulation of CSF-1 in the presence of RAW 264.7 cell CB." (PMID 19696929, 2009). "Cancer cells synthesize colony-stimulating factor 1 (CSF1) to stimulate macrophages." (PMID 40507830, 2025). "Cancer cells from growing ribociclib-resistant tumors modify the behavior of immune regulating myeloid cells, through production of diverse communications including CSF1, CLCF1, FGF, and TGF family members and interleukins 5/11/12." (PMID 40032842, 2025). "Furthermore, monocyte dynamics are reprogrammed in cancer patients through alterations in systemic cytokines, such as colony-stimulating factor 1 (CSF1), CSF2 and CSF3." (PMID 41444555, 2025). "However, increased Jun expression in response to certain agonists (e.g., PAUF, CSF1) in TME cells can result in unfavourable effects including increased cancer cell migration or release of immunosuppressive cytokines." (PMID 39859271, 2025). "Thus, blocking the CSF-1/CSF-1R signaling axis has emerged as a potential strategy for cancer immunotherapy." (PMID 39403370, 2024). "Targeting CSF-1/CSF-1R is one of the most well-known strategy to inhibit TAMs functions in cancer." (PMID 38554213, 2024). "Both preclinical and clinical studies have shown that targeting the CSF-1/CSF-1R axis can be a promising therapeutic strategy, as using antagonists and mAbs for CSF-1R have great potential to improve the outcome of patients with advanced cancer." (PMID 39003350, 2024). "This analysis suggests that targeting the CSF-1/CSF-1R signaling axis is a promising strategy for cancer treatment, and CSF-1R inhibitors have great potential to improve the prognosis of patients with advanced cancer." (PMID 39403370, 2024). "Following this, another signaling loop is activated as well: CA-MSCs secrete CCL5, which binds to CCR5 on the surface of cancer cells and triggers the expression of the chemokine colony stimulating factor-1 (CSF-1) on those cancer cells, which then induces macrophages and MDSCs migration." (PMID 38022534, 2023). "Similarly, inhibition of CSF-1 gene expression with antisense oligonucleotides or small interfering RNAs, suppressed tumor growth in mice xenografted with human cancer cells." (PMID 37046671, 2023). "Hence, our findings further provide a rationale for combining cancer vaccines with CSF1 targeting agents in the future." (PMID 37505292, 2023). "Thus, targeting the CSF-1/CSF1R pathway appears to represent an attractive therapeutic strategy in the treatment of cancers." (PMID 37143666, 2023). "In addition, activation of a paracrine loop also allows cancer cells that produce CSF-1 and TAMs that produce EGF to migrate together toward TMEM doorways." (PMID 37429944, 2023). "US clinical trials in cancer using Monoclonal antibodies targeting CSF-1 or CDF-1R." (PMID 37114134, 2023). "High expression of CSF1 correlates with poor prognosis in a variety of cancer types 6, 35-38." (PMID 35664070, 2022).
cancer (continued). "To further test the mechanisms of CSF1 enhancer function and determine if our observations about this enhancer are extensible to other cancer types, we surveyed the TCGA Pan-Cancer Atlas dataset to identify other types of cancer in which CSF1 is highly expressed." (PMID 35406623, 2022). "Both BMDM and iBMDM proliferation rates were significantly enhanced on exposure to A549 CM and AE17 CM, probably because of cancer cell-released various cytokines (e.g., macrophage colony-stimulating factor (M-CSF/CSF-1)) and soluble factors that affect macrophage differentiation and proliferation." (PMID 36311795, 2022). "With increasing cancer grade (Gleason 6-10), the expression of CSF1 and NOS3 increased." (PMID 36209194, 2022). "Macrophage colony-stimulating factor 1 (CSF1) secreted by cancer cells binds to its receptor (CSF1R) on the macrophage membrane, and in turn, activates the downstream signaling pathway responsible for the polarization of TAMs to the immunosuppressive phenotype." (PMID 35216342, 2022). "Eight cytokines (IL-1β, IL-6, IL-10, TGF-β, CCL2, CXCL8, CSF-1, and VEGF) were identified to have higher expression values in the high-risk group than in the low-risk group, which was relevant to the progression, invasion, and metastasis of cancers." (PMID 36120553, 2022). "Finally, we test our eRNA-dependent model of CSF1 enhancer function and demonstrate that our results are extensible to other forms of cancer." (PMID 35406623, 2022). "Similarly, in the circulation, the lack of changes in the half-lives of the increased numbers of monocytes in cancer suggest the presence of sufficient CSF1 to maintain their viability." (PMID 35159100, 2022). "Considering the complex relationship between CSF1/CSF-1R-expressing carcinoma cells and macrophages, synthesis of OPN is of particular interest since OPN is a chemoattractant for macrophage and regulates its adhesion, migration, differentiation, and production of cytokine." (PMID 36555673, 2022). "Indeed, cancer cell migration is enhanced by perivascular TAMs involving a paracrine loop of TAMs CSF1 secretion and epidermal growth factor (EGF) secretion by cancer cells." (PMID 33783686, 2021). "CSF1R, a receptor for colony stimulating factor 1, is overexpressed in many cancers." (PMID 34487971, 2021). "Collectively, blockade of the CSF-1/CSF-1R axis may be a potential strategy in cancer therapy, especially for TGCTs." (PMID 34178692, 2021). "Cancer cells secrete CSF-1 to activate CSF-1/CSF-1R pathway and TAM formation." (PMID 34575416, 2021). "Both GPA33 and CSF-1 show promising potential for targeted anti-cancer treatment." (PMID 33671266, 2021). "Phenotypic experiments proved that GAPLINC plays a role in promoting cancer through CSF1." (PMID 34722262, 2021). "Previous studies showed that CSF1 could act as a promoting regulator in variety of cancers, including RCC." (PMID 34722262, 2021). "Targeting the CSF1/CSF1R inhibitors has gained the most attention in this context with various approaches currently under clinical development for treatment of several cancer types including advanced castration-resistant prostate cancer (CRPC) with bone metastases." (PMID 34803925, 2021). "Therefore, blocking CSF‐1/CSF‐1R activation is becoming an important therapeutic strategy to inhibit cancer growth and metastasis." (PMID 33463063, 2021). "Thus, blocking CSF-1 and CSF-1R-mediated signaling can be a promising strategy for cancer immunotherapy." (PMID 34178692, 2021). "In contrast, mesenchymal cancer cells featuring elevated secretion of CSF-1 show opposite effects, indicating that stromal composition and its plasticity may be reflected by the differentiation grade of cancer cells." (PMID 32397303, 2020).